IL10 (interleukin 10)
Diseases named in the same sentence as IL10 in open-access papers (continued):
Sharing a sentence is not in itself a finding about the gene and the disease.
tumor (continued). "Flow cytometry analysis of tumor-derived single-cell suspensions showed that all treated groups, compared with control IgG-treated group, exhibited reversed immunosuppressive activity of tumor-associated Mφs, evidenced by the reduced populations of IL10+F4/80+ cells by up to 70%." (PMID 34103524, 2021). "Furthermore, IL-10 can kill monocytes/macrophages, suggesting that IL-10 can directly kill tumor cells as well as tumor-associated macrophages." (PMID 33912464, 2021). "Therefore, the different roles of IL-10 on tumor development are associated with different physiopathological states and the local environment." (PMID 33717103, 2021). "The probable reason for this effect might be stemmed from the impaired function of INF-α, which IL-10 can cause in the tumor microenvironment." (PMID 33692796, 2021). "To assess which factors present in the conditioned medium may regulate GITRL expression, we determined release of a panel of tumor-associated cytokines, namely TGFβ, IFNγ, IL-10, TNF and IL-2." (PMID 33538861, 2021). "A 14-day model of B16F10 melanoma growth using wildtype and C3−/− mice showed that smaller tumour development was associated with greater IL-10 expression in C3−/− CD8+ T cells, which were increased, while the numbers of CD45+ CD11b+ Gr1+ tumour infiltrating leukocytes remained comparable." (PMID 33494138, 2021). "They found TEM expressed significantly more IL-10 protein than TAM (tumor-associated macrophages)." (PMID 34198760, 2021). "Pearson correlation coefficients were calculated, and the results indicated that BGN presented the strongest correlations with TIIC markers for monocytes (CD86, CD115), tumor-associated macrophages (TAMs) (IL-10, CCL2, CD68), M2 macrophages (CD163, VSIG4, and MS4A4A) and Tregs (FOXP3, CCR8, TGFβ)." (PMID 35096572, 2021). "Moreover, the anti-tumor inflammatory activation of microglia was directly affected by reduced cell proliferation that was linked to TGFβ and IL-10 signaling mechanisms." (PMID 34566949, 2021). "Furthermore, MDSCs induce the immunosuppressive M2 macrophages by secreting IL-10, which, in turn, downregulates IL-12 production by tumor-associated macrophages (TAMs)." (PMID 34359568, 2021). "Tumor-associated macrophages (TAMs) are capable of promoting tumor growth and progression during almost all stages of cancers via the secretion of immunosuppressive factors like interleukin-10 (IL-10)." (PMID 34124046, 2021). "In the past, we showed that IL-10, secreted by tumor-associated macrophages, could reduce phosphorylated-p65-NFκB expression in splenocytes of tumor-bearing mice as part of the tumor evasion mechanism." (PMID 33330068, 2020). "However, despite conflicting evidences, high levels of serum IL-10 have been associated with poor prognosis in cancer patients across different tumor types including melanoma." (PMID 33077770, 2020). "Further, it is categorized as an immunogenic tumor as its lesions have been found to have signatures of several immune escape mechanisms such as the downregulated expression of HLA molecules, secretion of cytokines like IL-10, and loss of tumor-specific antigens." (PMID 32273881, 2020). "Particularly, aerosolization of CpG-ODN with Poly(I:C) into the bronchoalveolar space reduced the presence of M2-associated arginase- and IL-10-secreting macrophages in tumor-bearing lungs and increased the antitumor activity of aerosolized CpG-ODN alone against B16 lung metastases." (PMID 32093313, 2020). "Furthermore, tumor DCs that are deficient in LRP5/6 or β-catenin express markedly lower levels of IL-10 and are more potent in cross-priming CD8+ T cells." (PMID 32132993, 2020). "On the other hand, IL-10 has been classically associated with an immunosuppressive microenvironment and may promote tumor development and progression." (PMID 32733470, 2020).
tumor (continued). "The expression of TGFβ and IL-10, cytokines derived from tumor cells, is related to the differentiation of tumor-infiltrating immune cells, such as tumor-associated macrophages (TAMs) and neutrophils (TANs), into the tumor-promoting phenotype." (PMID 33321708, 2020). "In the course of hepatocellular carcinoma progression, PD-1 is strongly expressed by tumor-infiltrating B lymphocytes and interacts with PD-L1, expressed by tumor-associated macrophages, leading to IL-10 production by B lymphocytes, inhibition of TL cytotoxic activity and tumor expansion." (PMID 33381116, 2020). "IL-10 produced by tumor-associated-macrophage could also inhibit IL-12 production by DCs and alter their ability to mount antigen specific T cell responses." (PMID 33240930, 2020). "Current studies in tumor-associated B cells, such as the regulatory B cells, mainly focused on the secretion of IL-10 and TGF-β, which might contribute to the function of T cells and therapy effect of T cell-mediated immune response." (PMID 32580738, 2020). "Modify the tumor-immune microenvironment through the E-cadherin/β-catenin signaling pathway to cause cancer; induce Th2 immunity through the RORγτ+Treg cells, IL-10, and Th17 cells in the cervical epithelium." (PMID 33330121, 2020). "In HNSCC, TAMs generally show the tumor-promoting M2 phenotype that is associated with the production of the immunosuppressive cytokines IL-10 and TGF-β, and their presence in the tumor microenvironment is positively correlated with lymph node status and poor prognosis." (PMID 33042814, 2020). "As an immunosuppressive cytokine related to the tumor microenvironment, the elevation of IL-10 in ICI therapy might be caused by tumor evasion mechanisms that suppress the activation of T-cells." (PMID 32992737, 2020). "Furthermore, Tregs regulate various molecules, such as cytotoxic T-lymphocyte-associated antigen-4, IL2, and IL10, and promote tumor tolerance in the TME, making it a potential target for cancer treatment." (PMID 32707869, 2020). "Additionally, it is highlighted that the IL-10 rs1800872 G allele is associated with poorly differentiated tumor." (PMID 32744314, 2020). "In addition, the Chinese medicine formula that contains astragalus (Bu-Fei Decoction) shows that the connection between tumor-associated macrophages (TAMs) and cancer cells can be disrupted by inhibiting the expression of IL-10 and PD-L1 molecules." (PMID 32190660, 2020). "One of such immune subsets is the tumor-associated macrophages (TAMs) which are polarized into M2 macrophage phenotype by IL-10, TGF-β, IL-4, or IL-13 present in the TME, and drive tumor progression by supporting angiogenesis and recruitment of CD4+FoxP3+ T regulatory cells (Tregs)." (PMID 33117354, 2020). "Additionally, macrophages are considered the main source of IL-10 in WT mice which cause immunosuppression and lead to tumor progression." (PMID 32784928, 2020). "In addition, higher levels of inhibiting cytokines (e.g., interleukin 10) were present in the tumor microenvironment of low-risk patients." (PMID 32850416, 2020). "Notably, while IL-10+ Treg cells promote tumor growth and induce T cell exhaustion, deletion of IL-10 in Treg cells has been shown to cause a drastic reduction in the expression of PD-1, TIM3, and LAG3 in intra-tumoral CD8+ T cells." (PMID 32670290, 2020). "However, IL-4 and/or IL-10 alternatively activate macrophages and polarize them into tumor-associated macrophages, resulting in tumor promotion/progression." (PMID 32993179, 2020). "When correlating mRNA expression with overall survival rates in univariate analysis, high IL10 levels in both tumor and peritumoral samples were significantly associated with worse patient prognosis.In peritumoral samples, high expression levels of PD1 were also associated with worse survival." (PMID 32100077, 2020).
tumor (continued). "Like in AIT, IgG4 formed in tumor and tumor stroma is associated with chronic antigen challenge and with the Th2 cytokines IL-4 and IL-13, in combination with IL-10, released by Treg cells and M2-like macrophages in particular but also by the tumor cells themselves." (PMID 32708690, 2020). "Importantly, tumor-associated antigens such as 5-lipoxygenase (breast cancer; and placental growth factor (glioblastoma; have been shown to induce IL-10-production in tumor-infiltrating B cells in murine models." (PMID 33569063, 2020). "Also, plasma ANGPTL-4 level was positively associated with IL-10 and IL-15 contents in tumor and with IL-15 content in mesenteric adipose tissue." (PMID 31741709, 2019). "Thus, our findings suggest that IL-10 originating from tumor-associated macrophages' (TAMs) and the tumor cells would also likely play a significant role in the acquisition of the invasive features of LSCC." (PMID 31885577, 2019). "Promoter polymorphism of IL-10 may influence tumor development by altering its levels in serum or the TIME." (PMID 31769418, 2019). "Although the exact function of Treg cells in these tumor remains unknown, the inflammation-suppressive effect of Treg cells by producing IL-10 is widely believed to reduce the risk of CAC." (PMID 31798539, 2019). "This latter effect might be responsible for the recruitment of tumor-associated microglia/macrophage (TAM), which mediates tumor cell survival through secretion of IL-10 and Vascular-Endothelial Growth Factor (VEGF)." (PMID 30978987, 2019). "Also, the downregulation of the anti-inflammatory factors as IL-10 and IL-15 contribute for the development of the tumor and loss of body mass." (PMID 31741709, 2019). "Whereas others reported the production of immunosuppressive cytokines in different conditions and B cell subpopulations, we did not detect an upregulation of genes associated with immunosuppression in tumor-derived B cells, namely Il-12a, Ebi3 (which together form IL-35) and Il-10." (PMID 30972056, 2019). "B lymphocyte subtypes B10 and Breg, tumor-associated macrophages (TAMs), and myeloid-derived suppressor cells (MDSCs) produce immunosuppressive factors such as interleukin 10 (IL-10) and interleukin 12 (IL-12), which are used by malignant cells to hide from immunosurveillance." (PMID 31234497, 2019). "From another perspective, a more detailed understanding of the pro‐angiogenic activity and underlying mechanism of IL‐10 within the context of tumour development or any disease in parallel with angiogenesis and chronic inflammation also awaits further investigation." (PMID 31418859, 2019). "We hypothesized that the immunosuppressive environment is mediated by astrocyte/microglia crosstalk and JAK/STAT activation of tumor-associated astrocytes lead to a high level of IL10, which maintains the anti-inflammatory environment." (PMID 31186414, 2019). "C3-deficient mice are resistant to tumour development in a T cell- and IL-10-dependent manner." (PMID 30841875, 2019). "Tumor-associated macrophages (TAMs) and tumor cells themselves produce IL-10." (PMID 31412566, 2019). "Accumulating evidence suggests that M2 macrophages activated by cancer cells could promote activation of STAT3, triggering secretion of several cytokines (IL-6 and IL-10) and this eventually causes increased tumor growth and metastasis." (PMID 30791624, 2019). "IL10/EPHX2 double knockout mice also showed reduced IBD-associated tumor development." (PMID 31002701, 2019). "In the TME, several tumor and tumor-associated cells produce and secrete factors that directly or indirectly prevent NK cell activation, including interleukin (IL)-6, IL-10, transforming growth factor-β (TGF-β), prostaglandin E2 (PGE2), and idoleamine 2,3-dioxygenase (IDO)." (PMID 31616440, 2019).
tumor (continued). "Furthermore, the IL-17 production by all tumor-associated Treg compared to Treg from unaffected colon tissue was also similar, while IL-10 production by tumor-associated Treg was lower than in Treg from unaffected colon." (PMID 30651930, 2018). "The mechanism accounting for these findings remains largely undetermined, but may likely be implicated in the regulation of IL-10 expression and attenuation of tumor escape by IL-10-mediated immunosuppression." (PMID 29467923, 2018). "Inoculation of NC101 strain (a mouse isolate of pks-positive E.coli) increased colon inflammation and intestinal crypt proliferation in human CEACAM6-transgenic mice, and caused DNA damage in colonocytes and promoted tumor growth in AOM-treated IL-10(-/-) mouse models." (PMID 30413188, 2018). "Expression of IL-6 and IL-10 (macrophage-associated cytokines) in tumour tissue has only been determined in a few studies and using relatively small patient cohorts with limited information about prognostic significance (e.g. 108 invasive BC cases stained for IL-6 and other cytokines)." (PMID 29256156, 2018). "The fact that the ERS inhibition in our study with 4PBA led to IL-10 elevation was a significant finding because IL10 stimulated cytotoxicity in CD8+ cells and cancer cells treated with pegylated IL-10 led to tumor rejection, anti-tumor effects, and tumor-associated inflammation." (PMID 30326660, 2018). "Asialyl-agalactosyl IgG, as its effect on the activation of tumor-associated macrophages, upregulated tumor-associated macrophage-related cytokines including interleukin (IL)-4, IL-10, transforming growth factor (TGF)-β1, and tumor necrosis factor (TNF)-α, in macrophagic U-937 cells." (PMID 30469416, 2018). "Notably, ST2 deficiency resulted in lower IFN-γ, TNF-α, IL-10, and IL-17 production in tumor samples." (PMID 30112116, 2018). "IL-10 is a cytokine that regulates immune function, acting on a variety of immune cell subsets and playing a role in immune suppression in a variety of ways that can cause or prevent tumor immune escape." (PMID 30564277, 2018). "Further studies showed that IL-10 promoter polymorphisms were correlated with tumor progression and clinical outcomes in a number of cancers, such as breast cancer, squamous cell carcinoma (SCC) after renal transplantation, and non-small cell lung cancer (NSCLC)." (PMID 29732034, 2018). "In the tumor tissue, they caused an increase in the level of IL-10." (PMID 30037009, 2018). "As interleukins such as IL-4 and IL-10 can increase the level of M2 polarized macrophages, thus inhibiting the anti-tumor effect of non-neoplastic T-cells, Th2-associated cytokines can influence the tumor microenvironment to promote tumor progression." (PMID 29100307, 2017). "Under hypoxic conditions, HIF-1alpha leads to anupregulation of PD-L1 expression on MDSCs in the tumor microenvironment, thereby increasing interleukin (IL)-6 and IL-10 secretion from MDSCs, causing a MDSC-induced immunosuppression, T cell inactivation, and promoting tumor progression." (PMID 29250198, 2017). "Immune tolerance in the tumor microenvironment is closely involved in tumor progression caused by T-cell regulation via inhibitory signals of immune suppressive cytokine (IL-10), immune checkpoint molecules (programmed death-1 ligand 1 (PD-L1)), transforming growth factor-β, and prostaglandin E213." (PMID 28496107, 2017). "Finally, both IL-10 and IL-10R single nucleotide polymorphisms (SNPs) were involved in the pathogenesis of many tumours, including haematologic diseases." (PMID 29089667, 2017). "Interestingly, there were significant increases in Foxp3 and IL10 expression, which are associated with immunosuppression in the tumor microenvironment." (PMID 28620375, 2017). "CD5+ B cells have also been implicated in the suppression of anti-tumor immunity in humans through activation of Stat3, a transcription factor that may be involved in production of IL-10." (PMID 27437104, 2016).
tumor (continued). "As a final example, tumor-associated macrophages, which are programmed by cancer cells to assume phenotypes that support growth, have been shown, in some settings, to acquire a pro-proliferative phenotype in response to IL-10." (PMID 27491076, 2016). "Furthermore, IL10 levels obviously increase in cancer patients, and IL10 expression by tumor-associated macrophages is correlated with a poor prognosis." (PMID 26956044, 2016). "The presence of IL-10-producing DCs within tumors is associated with cancer antigen-specific immune responses and increased Treg populations, which have been implicated in playing a crucial role in the occurrence of tumor-mediated immune evasion." (PMID 27833081, 2016). "Here, we showed that IL10 deficiency inhibited the tumor secretion of TGF-β." (PMID 27075020, 2016). "pDCs also promote immunological tolerance by inducing IL-10-secreting regulatory T cells (Tregs) that may contribute to the enhanced tumor progression associated with tumor-infiltrating pDCs." (PMID 28018356, 2016). "Moreover, tumor-associated macrophages produced IL-10 and transforming growth factor-β, which suppressed Th1 lymphocytes, and recruited a Th2 response and regulatory T cells, promoting angiogenesis, wound healing, and pro-tumoral effectors." (PMID 26794215, 2016). "IL-10 associated with GBM is shown to enhance tumor growth, inhibit production of IFN-γ and tumor necrosis factor-alpha (TNF-α) by the immune system, downregulate expression of MHC class II in monocytes, and, via the co-stimulatory CD28-CD80/86 pathway, induce anergy in infiltrating T-cells." (PMID 26973839, 2016). "g., IL6 and TNF) that kill cancer cells; however, MΦ2 macrophages the predominant tumor associated macrophages in late stage cancers release anti-inflammatory IL-10, and a variety of growth factors (VEGF, FGF etc), that promote growth and vascularization of the cancer mass." (PMID 27231721, 2016). "Finally, it has been demonstrated that the number and activity of Treg increased by the soluble factors secreted from tumor associated MSCs, such as IL-10 and TGF-β45." (PMID 27329316, 2016). "Some studies have demonstrated that through depletion of some amino acids such as arginine and cysteine, and improve inhibitory cytokines such as IL-10 and IL-12, MDSCs can cause suppression of immune cells and stimulate immune regulators such as tumor-associated macrophages (TAMs)." (PMID 27780254, 2016). "Furthermore, another study has indicated that IL-10+ tumor associated macrophages promote the growth of tumors in an IL-10 dependent manner." (PMID 26509874, 2015). "In contrast, Th2 responses, associated with cytokines IL-4, IL-5, IL-6, and IL-10, suppress Th1 activity and may anergize effector T cells to tumor antigens." (PMID 26605345, 2015). "Therefore, IL-10 indeed associates with tumor-induced immune suppression and tolerance, and the presence of IL-10 in the microenvironment is positively associated with progression and development of cancer." (PMID 26684869, 2015). "These cells secrete anti-inflammatory cytokines (e.g., IL-10 and IL-1RA), promote wound healing, and tissue remodeling, but may also be associated with fibrosis and promote tumor progression." (PMID 26067369, 2015). "In addition, MDSCs secrete IL-10 and through membrane bound TGFβ, polarize tumor associated macrophages (TAMs) toward an M2- like anti-inflammatory phenotype." (PMID 25972872, 2015). "Moreover, in selective types of cancer, tumor-associated macrophages (TAM) produce IL10 and TGFβ, contributing to the general suppression of anti-tumor activities." (PMID 26477569, 2015). "For example, among cytokines, which are major immune players, IL6 and IL10 are known to cause immune suppression or tolerance, leading to tumor progression, whereas IL2, IL12, IL23, interferon (INF)-alpha and INF-gamma are crucial in immune activation, leading to tumor suppression." (PMID 26674411, 2015).